SLC25A52 (solute carrier family 25 member 52)
Description:
Mitochondrial membrane carrier protein that mediates the import of NAD(+) into mitochondria. Compared to SLC25A51, SLC25A52-mediated transport is not essential for the import of NAD(+) in mitochondria. The transport mechanism, uniport or antiport, its electrogenicity and substrate selectivity, remain to be elucidated.
Synonyms: MCART2
Tractability: Antibody: UniProt predicts a signal peptide or a membrane-spanning region.
Gene: Protein-coding gene on chromosome 18 (31,759,584 to 31,760,880, reverse strand). Ensembl gene ENSG00000141437.
Subcellular location: Mitochondrion inner membrane
Subcellular location (Human Protein Atlas): Mitochondria
Gene Ontology:
Molecular function: NAD transmembrane transporter activity
Biological process: mitochondrial NAD transmembrane transport
Cellular component: mitochondrion; mitochondrial inner membrane
Genetic constraint (gnomAD): Loss-of-function variants: 12 observed, 17.4 expected, observed/expected ratio (o/e) 0.69, 90% interval 0.44 to 1.12. The upper end of that interval is the gene's LOEUF score, 1.12, which puts it in group 4 of 6, group 1 being the genes least tolerant of losing a copy. Missense variants: 298 observed, 368.74 expected, observed/expected ratio (o/e) 0.81, 90% interval 0.73 to 0.89. Synonymous variants: 108 observed, 139.47 expected, observed/expected ratio (o/e) 0.77, 90% interval 0.66 to 0.91.
Homologues: Orthologues: macaque SLC25A52 (92% identical), dog SLC25A51 (92% identical), guinea pig Slc25a51 (86% identical), mouse Slc25a51 (85% identical), rat Slc25a51 (85% identical), rat Slc25a52 (82% identical), rat Slc25a51l1 (78% identical). Paralogues in human: SLC25A51 (96% identical), SLC25A13 (29% identical), SLC25A12 (28% identical), SLC25A21 (26% identical), SLC25A16 (25% identical), SLC25A39 (25% identical), SLC25A20 (25% identical), SLC25A22 (25% identical), SLC25A31 (24% identical), UCP3 (24% identical), SLC25A37 (24% identical), SLC25A40 (24% identical), and 37 more.
Diseases named in the same sentence as SLC25A52 in open-access papers:
SLC25A52 is named in the same sentence as 2 diseases in open-access papers, as found by Europe PMC text mining. Sharing a sentence is not in itself a finding about the gene and the disease. The quoted sentences say what the papers report.
non-small cell lung carcinoma (1 paper, 2021). A group of at least three distinct histological types of lung cancer, including non-small cell squamous cell carcinoma, adenocarcinoma, and large cell carcinoma. "For example, the highly differential model for SMG1 is sepsis, the model for SLC25a52 is secondary renal amyloidosis, and the model for Zbtb5 is non-small-cell lung cancer." (PMID 34440578, 2021).
SLC25A52 also shares sentences with these, for which no sentence is quoted: Sepsis (1 paper).